KHDC1L (KH domain containing 1 like)
Synonyms: RP11-257K9.7
Tractability: No criterion of Open Targets' tractability assessment is met for any kind of drug.
Gene: Protein-coding gene on chromosome 6 (73,223,544 to 73,225,770, reverse strand). Ensembl gene ENSG00000256980.
Subcellular location (Human Protein Atlas): Cytosol; Vesicles
Gene Ontology:
Molecular function: RNA binding
Cellular component: cytoplasm
Genetic constraint (gnomAD): Loss-of-function variants: 5 observed, 10.24 expected, observed/expected ratio (o/e) 0.49, 90% interval 0.25 to 1.03. The upper end of that interval is the gene's LOEUF score, 1.03, which puts it in group 4 of 6, group 1 being the genes least tolerant of losing a copy. Missense variants: 165 observed, 146.05 expected, observed/expected ratio (o/e) 1.13, 90% interval 1 to 1.29. Synonymous variants: 62 observed, 52.37 expected, observed/expected ratio (o/e) 1.18, 90% interval 0.96 to 1.46.
Homologues: Orthologues: chimpanzee KHDC1L (98% identical), macaque KHDC1L (90% identical), rat Khdc1 (52% identical), mouse Khdc1b (48% identical), rat LOC134483627 (48% identical), mouse Khdc1a (48% identical), mouse Khdc1c (48% identical). Paralogues in human: KHDC1 (84% identical), DPPA5 (21% identical).
Diseases named in the same sentence as KHDC1L in open-access papers:
KHDC1L is named in the same sentence as 12 diseases in open-access papers, as found by Europe PMC text mining. Sharing a sentence is not in itself a finding about the gene and the disease. The quoted sentences say what the papers report.
HCMV infection (1 paper, 2022). "Transcripts specifically induced by HCMV infection of TOs included H3Y1 (H3.Y Histone 1), KHDC1L (KH Domain Containing 1 Like), several members of the PRAME Family (PRAMEF2, 8, 12, 14, and 20), and TRIM49A and B (Tripartite Motif Containing 43)." (PMID 35975985, 2022).
oral cancer (1 paper, 2023). "Consistent with the bioinformatics results, RT-PCR experiments verified that expression of KHDC1L was higher in human oral cancer cells (SCC9, CAL27) than human oral epithelial cell (HOK) (P < 0.05)." (PMID 36734243, 2023). "Our study confirmed that KHDC1L was significantly overexpressed in HNSCC tissues and oral cancer cells (SCC9, CAL27), and revealed its corresponding function in promoting cell proliferation and anti-apoptosis in HNSCC." (PMID 36734243, 2023).
osteoarthritis (1 paper, 2023). A noninflammatory degenerative joint disease occurring chiefly in older persons, characterized by degeneration of the articular cartilage, hypertrophy of bone at the margins and changes in the synovial membrane. "KHDC1L expression was elevated in synovial tissue of patients with osteoarthritis, and downregulation of its expression inhibited synovial cell proliferation." (PMID 36734243, 2023). "As shown in a previous study, upregulated KHDC1L was found to be correlated with osteoarthritis and managed to promote synovial cell proliferation, while its expression and function in cancer remained entirely unclear." (PMID 36734243, 2023). "As a novel KHDC1 member, only one study is currently available in osteoarthritis synovial cells to unveil KHDC1L’s function of promoting proliferation." (PMID 36734243, 2023).
ovarian serous cystadenocarcinoma (1 paper, 2023). A malignant serous cystic epithelial neoplasm arising from the ovary. "In addition, patients with high-level KHDC1L generally possessed shortened overall survival (OS) in sarcoma (SARC), while a longer OS in ovarian serous cystadenocarcinoma (OV)." (PMID 36734243, 2023).
Testicular Germ Cell Tumours (1 paper, 2023). "Hereby, we performed a pan-cancer analysis on KHDC1L through GEPIA database, to find KHDC1L expression substantially elevated in HNSCC and Testicular Germ Cell Tumours (TGCT)." (PMID 36734243, 2023).
thyroid cancer (1 paper, 2023). "In accordance with GSEA, pathway in cancer and thyroid cancer pathways were enriched in the KHDC1L overexpression group." (PMID 36734243, 2023).
cancer (1 paper, 2023). A tumor composed of atypical neoplastic, often pleomorphic cells that invade other tissues. "In summary, our study took the lead in identifying KHDC1L as a novel molecular biomarker in HNSCC, contributing to an effective target against cancer." (PMID 36734243, 2023).
infection (1 paper, 2023). The state of being infected such as from the introduction of a foreign agent such as serum, vaccine, antigenic substance or organism. "In particular, hCMV induced H3Y1 (H3.Y Histone 1), KHDC1L (KH Domain Containing 1 Like), members of the PRAME family, and TRIM49A and B (Tripartite Motif Containing 43) in trophoblast but not decidual organoids, potentially explaining the relative resistance to infection in the former." (PMID 36908829, 2023).
tumour (1 paper, 2023). "Nevertheless, to the best of our knowledge, the role of KHDC1L in human tumour is yet to be fully explored." (PMID 36734243, 2023).
KHDC1L also shares sentences with these, for which no sentence is quoted: facioscapulohumeral muscular dystrophy (1 paper); head and neck squamous cell carcinoma (1); sarcoma (1).